SEPSECS (Sep (O-phosphoserine) tRNA:Sec (selenocysteine) tRNA synthase)
Description:
Converts O-phosphoseryl-tRNA(Sec) to selenocysteinyl-tRNA(Sec) required for selenoprotein biosynthesis.
Synonyms: LP; SLA; SLA/LP; SLA-p35; SecS; PCH2D
Tractability: Small molecule: a structure with a bound ligand is known. PROTAC: ubiquitination databases record sites on it; its protein half-life has been measured.
Gene: Protein-coding gene on chromosome 4 (25,120,014 to 25,160,550, reverse strand). Ensembl gene ENSG00000109618.
Subcellular location: Cytoplasm
Subcellular location (Human Protein Atlas): Vesicles
Pathways (Reactome):
Metabolism: Selenocysteine synthesis
Gene Ontology:
Molecular function: O-phosphoseryl-tRNA(Sec) selenium transferase activity; protein binding; tRNA binding; transferase activity
Biological process: conversion of seryl-tRNAsec to selenocys-tRNAsec; selenocysteine incorporation; selenocysteine biosynthetic process; selenium compound metabolic process
Cellular component: cytoplasm; cytosol; transferase complex; nucleus
Genetic constraint (gnomAD): Loss-of-function variants: 31 observed, 38.19 expected, observed/expected ratio (o/e) 0.81, 90% interval 0.61 to 1.1. The upper end of that interval is the gene's LOEUF score, 1.1, which puts it in group 4 of 6, group 1 being the genes least tolerant of losing a copy. Missense variants: 492 observed, 520.6 expected, observed/expected ratio (o/e) 0.95, 90% interval 0.88 to 1.02. Synonymous variants: 177 observed, 178.55 expected, observed/expected ratio (o/e) 0.99, 90% interval 0.88 to 1.12.
Homologues: Orthologues: chimpanzee SEPSECS (99% identical), macaque SEPSECS (98% identical), pig SEPSECS (95% identical), dog SEPSECS (94% identical), rabbit SEPSECS (91% identical), guinea pig SEPSECS (89% identical), mouse Sepsecs (88% identical), rat Sepsecs (87% identical), tropical clawed frog sepsecs (78% identical), zebrafish sepsecs (73% identical), Drosophila melanogaster SecS (45% identical), Caenorhabditis elegans secs-1 (41% identical).
Diseases named in the same sentence as SEPSECS in open-access papers:
SEPSECS is named in the same sentence as 27 diseases in open-access papers, as found by Europe PMC text mining. Sharing a sentence is not in itself a finding about the gene and the disease. The quoted sentences say what the papers report.
pontocerebellar hypoplasia type 2D (5 papers, 2014 to 2024). Any non-syndromic pontocerebellar hypoplasia in which the cause of the disease is a mutation in the SEPSECS gene. "Recently, two research groups reported that four distinct mutations in human SEPSECS caused congenital cerebellar atrophy termed pontocerebellar hypoplasia type 2D (PCH2D)." (PMID 27576344, 2016). "Recently, a syndrome called progressive cerebello-cerebral atrophy (PCCA) was described which is caused by mutations in the selenocysteine synthase (SEPSECS) gene." (PMID 24599700, 2014). "Mutations in the SEPSECS gene are associated with pontocerebellar hypoplasia type 2D." (PMID 29464431, 2018). "SEPSECS mutations are associated with pontocerebellar hypoplasia type 2D (PCH2D)." (PMID 29464431, 2018). "Four SNPs mapped to SYCP2L, VAV, SEPSECS, and TMPRSS15 are known to be associated with age-related hearing impairment, multiple sclerosis, pontocerebellar hypoplasia type 2, enterokinase deficiency, respectively." (PMID 38291454, 2024). "Wirth and colleagues also noted striking parallels between their Trsp mutant mice and human patients with pontocerebellar hypoplasia type 2D (PCH2D, OMIM #613811), a syndrome caused by deleterious variants in the SEPSECS gene, which encodes a protein essential to selenoprotein biosynthesis." (PMID 30921410, 2019).
Cerebellar atrophy (2 papers, 2016 to 2025). Cerebellar atrophy is defined as a cerebellum with initially normal structures, in a posterior fossa with normal size, which displays enlarged fissures (interfolial spaces) in comparison to the foliae secondary to loss of tissue. "Currently, there are 12 known SEPSECS mutations that have contributed to disorders of cerebellar atrophy causing much ambiguity in the literature regarding the nomenclature of SEPSECS phenotypes." (PMID 27576344, 2016). "Variants in genes involved in selenoprotein translation, such as SEPSECS and EEFSEC, can lead to progressive cerebellar atrophy, demonstrating the vital role of selenoproteins in maintaining cerebellar function." (PMID 40652205, 2025).
developmental delay (2 papers, 2023 to 2024). "In humans, carriers of mutations in these genes (including SECISBP2, TRU-TCA1-1, and SEPSECS) display the severe multisystem phenotypes of global developmental delay with features of myopathy and cerebellar and optic atrophy." (PMID 37108730, 2023).
epilepsy (2 papers, 2014 to 2024). A brain disorder characterized by episodes of abnormally increased neuronal discharge resulting in transient episodes of sensory or motor neurological dysfunction, or psychic dysfunction. "PCH2D caused by SEPSECS mutations defined as contractures, sleep disturbances, irritability, edema of face and limbs, polyneuropathy, optic atrophy, microcephaly, epilepsy, nystagmus, and intellectual disability." (PMID 38622473, 2024). "Epilepsy and cerebellar hypoplasia are among the phenotypes of children afflicted with mutations in PCCA due to mutations in the SEPSECS gene." (PMID 24599700, 2014).
Intellectual disability (2 papers, 2024). "We identified two patients (case 4,5) with novel homozygous variants in SEPSECS (c.208T > C; p.C70R and c.1274A > G; p.H425R), both presenting with developmental and motor delay and intellectual disability." (PMID 38347586, 2024).
microcephaly (2 papers, 2024). A congenital or acquired developmental disorder in which the circumference of the head is smaller than normal for the person's age and sex. "A patient carrying a homozygous noncoding variant in the SEPSECS (c.114 + 3A > G) gene presented with term pregnancy, microcephaly, development delay, paraplagia, hypertonia, and spastic gait disorder." (PMID 38622473, 2024).
breast carcinoma (1 paper, 2024). "Overall, these in vivo results demonstrate that the expression of SEPHS2 and SEPSECS is less critical for mammary breast tumour growth than for breast cancer cells to survive in the bloodstream and colonise the lungs." (PMID 39433871, 2024).
cerebellar ataxia (1 paper, 2018). A neurological syndrome characterized by clumsy and uncoordinated movement of the limbs, trunk, and cranial muscles. "Here, we report a 23-year-old woman with slowly progressive cerebellar ataxia and cognitive impairment, in whom a homozygous missense mutation in the SEPSECS gene (c.1321G>A; p.Gly441Arg) was identified with whole exome sequencing." (PMID 29464431, 2018).
mammary tumours (1 paper, 2024). "In line with the working model proposed, the deletion of SEPHS2 and SEPSECS does not affect the proliferation of TNBC cultured at high density, and a transient interference with their expression does not appreciably delay the growth of orthotopic mammary tumours." (PMID 39433871, 2024).
pontocerebellar hypoplasia (1 paper, 2024). Pontocerebellar hypoplasias (PCH) are a rare heterogeneous group of diseases characterized by hypoplasia and atrophy and/or early neurodegeneration of the cerebellum and pons. "Two variants in SEPSECS (c.1274A > G:p.H425R) and TBC1D23(c.458T > C:p.M153T), had been reported in gnomAD or ExAC databases; however, no publications have ever reported the pathogenicity of these variants in pontocerebellar hypoplasia." (PMID 38347586, 2024).
cancer (3 papers, 2021 to 2025). A tumor composed of atypical neoplastic, often pleomorphic cells that invade other tissues. "Indeed, the interference with SEPHS2 or SEPSECS, enzymes of the selenocysteine biosynthesis pathway, strongly impairs the lung seeding of cancer cells injected into the bloodstream." (PMID 39433871, 2024). "We also recently showed that CRISPR disruption of selenocysteine biosynthesis machinery (SEPSECS, PSTK) hypersensitizes cancer cells against the lipid prooxidant tert-butyl hydroxide (TBH)." (PMID 33672555, 2021).
neurological disorders (3 papers, 2016 to 2024). "Our study facilitates understanding of these childhood neurological disorders by demonstrating that disease-causing SEPSECS mutations destabilize protein structure and increase the propensity of SepSecS to misfold." (PMID 27576344, 2016). "Moreover, the study identified DRD3 and SEPSECS as critical players in seizures, shedding light on their possible roles in neurological disorders." (PMID 39635461, 2024). "Both LGI2 and SEPSECS are essential genes related to neurological disorders, and they could affect development of the early nervous system." (PMID 35372529, 2022).
neurodevelopmental disorder (1 paper, 2023). A behavioral and cognitive disorder with onset during the developmental period that involves impaired or aberrant development of intellectual, motor, or social functions. "Pathogenic mutations in selenocysteine synthase (SEPSECS) cause neurodevelopmental disorders." (PMID 36952494, 2023).
SEPSECS also shares sentences with these, for which no sentence is quoted: optic atrophy (2 papers); age-related hearing impairment (1); Autoimmunity (1); Cerebellar hypoplasia (1); Cognitive impairment (1); enterokinase deficiency (1); Hypertonia (1); Hypotonia (1); Motor delay (1); multiple sclerosis (1); myopathy (1); Nystagmus (1); polyneuropathy (1); Progressive encephalopathy (1).